CALR (calreticulin)
Diseases named in the same sentence as CALR in open-access papers (continued):
Sharing a sentence is not in itself a finding about the gene and the disease.
tumor (continued). "These therapeutic modalities promote immunogenic cell death, enhancing tumor-associated antigen presentation and stimulating the release of damage-associated molecular patterns (DAMPs), including ATP, HMGB1, and calreticulin (CRT), thereby facilitating immune cell recruitment and activation." (PMID 41377584, 2025). "ICD occurs with CALR exposure on dying cell surfaces, providing an “eat me” signal to phagocytic cells, while the release of ATP acts as a “find me” signal, both of which together promote DC and macrophage infiltration at the tumor sites." (PMID 40532661, 2025). "It induces calreticulin transfer to the cell surface, which could activate macrophages and mature DC, leading to the activation of anti-tumor T cells by promoting antigen presentation." (PMID 40055311, 2025). "However, calreticulin is also abundantly expressed on the surface of tumor cells and further translocates to the cell surface during the apoptosis of tumor cells." (PMID 38835772, 2024). "Elevated CALR was correlated with favorable prognosis in distinct tumor types." (PMID 39749345, 2024). "JAK2 (Janus kinase 2; located on chromosome 9p24), MPL (myeloproliferative leukemia virus oncogene; located on chromosome 1p34), and CALR (calreticulin; located on chromosome 19p13.2) are specific somatic driver mutations that have been described in the major part of BCR-ABL–negative neoplasms." (PMID 38541232, 2024). "Moreover, the immunogenic cell death (ICD) effect induced by internalized DOX exposes calreticulin (CALR) on tumor cells, resulting in an “eat me” signal and increasing phagocytosis." (PMID 39334825, 2024). "Calreticulin is an endoplasmic reticulum-associated protein that is exposed on the surface of dying tumor cells after non-thermal histotripsy treatment." (PMID 38543305, 2024). "Cell cycle machinery is seen in essentially all tumor types and represents a driving force of tumorigenesis; however, to the best of our knowledge, no data show the impact of mutated CALR on cell cycle progression in the context of oxidative stress." (PMID 39337361, 2024). "Since C + D treatment activated the eIF2α phosphorylation and induced CALR exposure, we wondered whether C + D treatment suppresses tumor initiation and progression in a PERK/eIF2α-dependent fashion." (PMID 39090653, 2024). "Moreover, the secretion of high-mobility group box 1 (HMGB1) and calreticulin (CALR) from tumor cells induced TAMs’ M1-type polarization, dendritic cell (DC) maturation, and CD8-positive T-cell activation, resulting in a prolonged and enhanced immune response." (PMID 39457052, 2024). "A strategy for modeling this type of preclinical assessment would be the co-culture of ex vivo resected tumors with autologous NK cells to ascertain if the mere presence of an increasing NK cell population would be sufficient for clearance of CALR-expressing tumor cells." (PMID 38786045, 2024). "Previous studies have shown that ICP (e.g., PD-L1 and TIM-3) and ICD regulators (e.g., CALR) play important roles in regulating host anti-tumor immunity, thereby influencing the efficacy of mRNA vaccines, highlighting the link between pyroptosis and immune regulation." (PMID 38166691, 2024). "Dysregulation of CALR can impair this immune recognition, leading to immune evasion by tumor cells." (PMID 39469643, 2024). "Separately, the ER-resident chaperone calreticulin, which is connected to both immunogenic cell death and the localization of calreticulin on the surfaces of tumor cells, has been localized to the cell surface in tumor cells." (PMID 38672148, 2024). "The CALR is translocated to cell membrane surface when tumor cells undergo ICD15." (PMID 38370371, 2024). "Furthermore, SB633825 also significantly induced tumor cell apoptosis and CALR exposure in two AML patients." (PMID 39555062, 2024). "However, calreticulin expression at the tumor site is variable and, as such, often suboptimal in initiating a robust antitumor immune response." (PMID 38593053, 2024).
tumor (continued). "Given the impressive adsorption increase observed in the presence of fluorine in the current study, fluorine could further be used as a way of increasing calreticulin expression at the tumor site." (PMID 38593053, 2024). "Through Fcγ receptors on the surface of tumor cells, like CD20 and calreticulin, M1 macrophages may recognize and target tumor cells, which facilitates the phagocytosis of tumor cells by M1 macrophages." (PMID 39309874, 2024). "Simultaneously, numerous DAMP signals (such as calreticulin and high mobility group protein 1), inflammatory factors (such as interferons and interleukins) and tumor antigens are present in a spatiotemporally dependent manner, corresponding to the specific antitumor immune response." (PMID 39916954, 2024). "Furthermore, tumor cells were infected and studied for the surface expression of the ‘eat-me’-signal calreticulin (CALR) and the ‘don’t-eat-me’-signal CD47." (PMID 38357194, 2024). "We herein demonstrate that XVir-infected tumor cells upregulate both CALR and CD47." (PMID 38357194, 2024). "Additionally, inhibiting eIF2α phosphorylation by pharmaceutical or genetic methods abolished C + D-induced CALR exposure in vitro and attenuated the anti-tumor efficiency of C + D treatment in vivo." (PMID 39090653, 2024). "Currently, there are two pathways believed to promote tumor formation: the exogenous pathway, in which inflammation increases the risk of tumor formation, and the endogenous pathway, in which driver gene mutations such as JAK2, MPL, and CALR lead to the formation of an inflammatory microenvironment." (PMID 38348158, 2024). "In general, tumor cells induced by apoptosis can release DAMPs in the following order: (i) pre-apoptotic exposure of intracellular calreticulin to the cell membrane surface (ecto-CRT), (ii) early-apoptotic secretion of ATP, and (iii) post-apoptotic release of high-mobility group box 1 (HMGB1)." (PMID 39339179, 2024). "However, the effects of CALR on angiogenesis in tumor models have demonstrated that CALR undergoes N-terminal cleavage to generate the CALR fragment, vasostatin, that acts as an inhibitor of angiogenesis by preventing endothelial cell adhesion." (PMID 37692787, 2023). "Given the high immunogenicity of the mutations, and the identification of CALRmut specific T-cell memory responses in healthy donors, which suggest a defect in the tumor immune surveillance in CALRmut patients, we conducted a phase I clinical vaccination trial against mutant CALR (NCT 03566446)." (PMID 37662956, 2023). "There is a significant correlation between CALR and tumor-infiltrating immune cells." (PMID 36907982, 2023). "In line with the signature prognostic value, from the STRING network analysis emerged an implication of EBF1, MYO6, and CALR in the regulation of tumor progression together with the control of B lymphocyte gene transcription, intracellular vesicle transport and protein folding." (PMID 38035116, 2023). "The intracellular functions of CALR as a crucial regulator of Ca2+ homeostasis and the integrin-dependent signaling is probably required for tumor progression which therefore implies that CALR expression is robustly related to prompt tumor progression and poor prognosis in the nuclear DAMPs subtype." (PMID 37033966, 2023). "Among the HDP, some have been reported as ICD inducers, such as LTX-315 which, in addition to its effect in reducing pro-tumour immune cells, has also been reported to induce the emission of DAMPs (calreticulin, HMGB1 and ATP) and to induce in vivo myeloid and T lymphocyte tumour infiltration." (PMID 38077402, 2023).
tumor (continued). "In addition, calreticulin participates as initiator of endoplasmic reticulum stress in tumor cells and promotion of immunogenic cell death and removal by macrophages." (PMID 36993959, 2023). "RT-injured tumor and tumor-infiltrating cells release intracellular molecules known as damage-associated molecular patterns (DAMPs), or alarmins, including high-mobility group box 1 (HMGB1), ATP, and calreticulin." (PMID 36831435, 2023). "The exposure of cell surface calreticulin suggests the induction of immunogenic cell death which may promote anti-tumour immune responses." (PMID 37582853, 2023). "Together with the tumor-suppressing proteins such as CALR, ENO1, HSP, MSN, and UBC, which were enriched in tumor-suppressive CM, six recombinant proteins, such as HISTONE H4, PPIB, GJA1, CPE, S100A11, and PCOLCE, were identified as extracellular tumor-suppressing proteins." (PMID 36943734, 2023). "Hence, when the nanoparticle surface is modified with the “eat me” signal and calreticulin, they can be taken up more effectively by tumor cells and MDSCs." (PMID 37808190, 2023). "Notably, the level of CALR transcripts was elevated in OS tissues, together with other tumor-suppressing proteins, including histone H4, and PCOLCE." (PMID 36943734, 2023). "In contrast to free photosensitizers 36, inorganic nanoparticles with a diameter of 25 nm coated with lipid-anchored photosensitizers enhance the exposure of calreticulin on the surface of tumor cells and infiltration of immune cells when combined with infrared light irradiation." (PMID 37808190, 2023). "PCL@O2 containing Ce6 as the sonosensitizer and PFH as O2 reservoir, was synthesized as an augmented SDT nanoplatform and showed increased ROS generation to raise effective apoptosis of tumor cells, which also exposed more calreticulin to induce stronger immunogenic cell death (ICD)." (PMID 37051250, 2023). "When tumor cells undergo ICD, they release a variety of tumor-associated antigens and damage-associated molecular patterns (DAMPs), such as high mobility group protein 1 (HMGB1), calreticulin (CRT), adenosine-triphosphate (ATP) and heat shock protein (HSP90α)." (PMID 38106403, 2023). "In addition to calreticulin, T. cruzi possesses other specific components capable of exerting anti-tumor effects." (PMID 38274735, 2023). "Irradiation could rescue the ecto-calreticulin expression of tumor cells and improve phagocytosis to overcome ICB resistance." (PMID 36635765, 2023). "Interestingly, various chemotherapeutics led to the secretion of danger signals such as CALR which showed various tumor-promoting effects in BC and has been recently addressed as a biological marker of BC." (PMID 37762557, 2023). "Primarily used in the treatment of solid tumors such as melanoma, CIRT promotes tumor immunogenicity by enhancing the translocation of calreticulin to the plasma membrane, enhancing the release of HMGB1 and ATP, and promoting an IFN1 response, all major hallmarks of ICD." (PMID 37626741, 2023). "The exposure of calreticulin on the cell surface can stimulate DCs to phagocytize tumor cells." (PMID 37124541, 2023). "These are characterized by calreticulin (CALR), myeloproliferative leukemia virus proto-oncogene (MPL) and the tyrosine kinase Janus kinase 2 (JAK2) mutations, eventually establishing a hyperinflammatory tumor microenvironment (TME)." (PMID 36910610, 2023). "The N-terminal of T. cruzi calreticulin has the potential to directly interact with epithelial cells, inhibiting pro-angiogenic molecules, thereby resisting tumor angiogenesis, reducing oxygen and nutrient supply to tumors, and increasing the accumulation of metabolic waste products." (PMID 38274735, 2023). "In this study we aimed at identifying whether T cells specific to mutant CALR enrich in the bone marrow after therapeutic cancer vaccinations, as homing of T cells to the tumor microenvironment is important to attain a response to cancer immune therapy." (PMID 37662956, 2023).
tumor (continued). "This biomimetic delivery system induces ICD by using EPI as an ICD inducer, Gox and hemin to generate ROS (which strengthens the ICD effect), and calreticulin-rich membrane as an “eat me” signal to promote the presentation of antigens by DCs (to invoke the tumor-immunity cycle)." (PMID 37376125, 2023). "Calreticulin’s action on tumor-invaded bone and its interaction with CD47." (PMID 36943734, 2023). "Consequently, cell surface calreticulin expression on tumor cells positively correlates with degree of anti-CD47 activity." (PMID 37468567, 2023). "As the presence of tumor specific T cells in the tumor microenvironment is necessary to attain a clinical response to cancer immune therapy, we investigated if T cells specific for mutant CALR enriched in the bone marrow after completion of therapeutic cancer vaccines." (PMID 37662956, 2023). "For instance, nanoparticles can be designed to be sensitive to specific wavelengths of light or temperatures, synergistically producing ICD-inducing effects, thereby amplifying the exposure of calreticulin on the surface of tumor cells and the infiltration of immune cells." (PMID 37808190, 2023). "In addition to impaired antigen presentation and T‐cell priming, mutations in CALR also subvert cellular immunity via a specific mechanism, as the normal CALR protein has a key role in tumour immunosurveillance." (PMID 34618358, 2022). "The results showed that inhibiting the expression of the ICD-related genes CDK12/13 could release HMGB1 and translocate calreticulin, and promote T cell dependent tumor inhibition." (PMID 36437951, 2022). "Anthracyclines can induce the translocation of calreticulin from the cytoplasm to cell surface in tumour cells, which leads to their recognition by dendritic cells (DCs) and tumour antigen processing and presentation to CD4+ T and CD8+ T cells, thereby stimulating the antitumour immune response." (PMID 35665592, 2022). "First, after oxaliplatin enters tumor cells, it causes endoplasmic reticulum stress, and calreticulin (CRT) in the endoplasmic reticulum lumen is translocated to the cell membrane and exposed on the surface of tumor cells, triggering dendritic cells (DCs) and macrophages to engulf tumor cells." (PMID 36003374, 2022). "Moreover, the levels of the immunogenic cell death markers, HMGB1 and calreticulin, were also remarkably upregulated in LP-treated apoptotic tumor cells compared with some other TLR agonists in vitro." (PMID 35764365, 2022). "We assessed whether sustained release of Dox resulted in ICD by profiling calreticulin expression on tumor cells after treatment." (PMID 35780226, 2022). "It has also been proposed that CALR acts as a key regulator of ER homeostasis and this may be partially required for tumor progression." (PMID 36386817, 2022). "The pathway of ICD-induced tumour cell death relies on damage-associated molecular patterns (DAMPs) such as heat shock proteins (HSPs), high mobility group box 1 (HMGB1) and calreticulin (CRT), making tumour cells a “therapeutic vaccine” that can induce anti-tumour immunity." (PMID 36159787, 2022). "Lastly, we analyzed the correlation between CALR and immune infiltration levels in tumor microenvironments in KIRC using the TIMER2.0 database with single-sample GSEA (ssGSEA), and confirmed the results using the Gene Expression Profiling Interactive Analysis (GEPIA) database." (PMID 36338983, 2022). "Like protons and photons, heavy ions can induce changes in the tumor cell membrane surface, such as increased ecto-calreticulin exposure, which makes tumor cells more easily recognized and cleared by the immune system and plays an important role in the activation of antitumor immunity." (PMID 35216430, 2022). "Interestingly, the CALR expression was significantly higher in SKCM metastasis than in SKCM tumor tissues, and was significantly lower in THCA than in adjacent normal tissues." (PMID 36338983, 2022).
tumor (continued). "In addition, as an important member of DAMP, the CALR molecule acts as an important “eat me” signal against the “don’t eat me” signal of tumor cells to promote antigenic uptake and immune recognition of APC." (PMID 36212143, 2022). "Moreover, the intensity of CALR staining in tumor tissues increased with invasion depth and metastatic lymph node." (PMID 35641480, 2022). "Napabucasin heightened the levels of calreticulin and ERp57 in tumour cells." (PMID 35665592, 2022). "ECT induces ICD through the liberation of ATP, HMGB1, and calreticulin, which in turn might increase the tumor infiltration of several immune cells, including CD8+ T cells and NK cells." (PMID 35740542, 2022). "For instance, in orthotopic mouse glioma models, NDV immunotherapy has been shown to increase calreticulin translocation to the cell surface and extracellular accumulation of high mobility group box 1 and a tumor-specific immune response and long-term tumor regulation." (PMID 35910836, 2022). "Increased CALR expression may suppress ER stress in tumor cells, thereby exerting an inhibitory effect on induced ICD." (PMID 36386817, 2022). "Further in vivo assays demonstrated that CALR depletion inhibits tumor growth." (PMID 35264066, 2022). "In subcutaneous and orthotopic transplantation mouse tumour models, the STAT3 inhibitor napabucasin prevented tumour growth and induced the expression of calreticulin and the protein disulfide isomerase family A member 3 (PDIA3; also known as ERp57) but suppressed that of CD47 and GLUT1." (PMID 35665592, 2022). "Tumor cells express calreticulin and secreted ATP as well HMGB1; NK and granulocyte recruitment." (PMID 35640930, 2022). "The expression level of CALR is positively correlated with tumor size and status of metastasis." (PMID 36136972, 2022). "Recent advances have demonstrated that some chemotherapeutics including PTX could act as immunogenic cell death inducers by arousing calreticulin exposure on tumor cell surface and the release of high mobility group box 1 from tumor cells." (PMID 36303207, 2022). "In addition to the immunogenic effects of MPLA, DOX has been shown to increase tumor immunogenic cell death through a variety of mechanisms including the exposure of calreticulin, which stimulates dendritic cell antigen presentation." (PMID 33532588, 2021). "Typically, immunogenic cell death is associated with expression of surface calreticulin, release of HMGB1, release of ATP, whereas vaccination and tumor re-challenge assays have been considered as a standard in vivo approach to validating immunogenic cell death inducers." (PMID 34359580, 2021). "This suggests that vaccines directed against mutant CALR may be used with other cancer therapeutic modalities to enhance the anti-tumor immune response." (PMID 33718228, 2021). "This indicates different correlation between CALR and tumor progression in different tumors." (PMID 34910788, 2021). "Previous findings have demonstrated that conventional therapies, such as chemotherapy‐mediated upregulation of cell surface calreticulin and radiotherapy‐induced inflammation, increased the sensitivity of the tumour to macrophages, all of which contributed to the outcomes of anti‐CD47 treatment." (PMID 33449453, 2021). "In stressed or dying cells, CALR exposed on the cell surface serves as a phagocytic signal to dendritic cells (DCs), resulting in the engulfment of cancer cells by DCs, tumor antigen presentation, and anti-cancer cytotoxic T lymphocyte-specific immune responses." (PMID 34944879, 2021).